SPPL3 (signal peptide peptidase like 3)
Description:
Intramembrane-cleaving aspartic protease (I-CLiP) that cleaves type II membrane protein substrates in or close to their luminal transmembrane domain boundaries. Acts like a sheddase by mediating the proteolytic release and secretion of active site-containing ectodomains of glycan-modifiying glycosidase and glycosyltransferase enzymes such as MGAT5, B4GAT1 and B4GALT1. Catalyzes the intramembrane cleavage of the envelope glycoprotein gp130 and/or the leader peptide gp18LP of the simian foamy virus independent of prior ectodomain shedding by furin or furin-like proprotein convertase (PC)-mediated cleavage proteolysis. May also have the ability to serve as a shedding protease for subsequent intramembrane proteolysis by SPPL2A and SPPL2B of the envelope glycoprotein gp130. Plays a role in the regulation of cellular glycosylation processes. Required to link T-cell antigen receptor (TCR) and calcineurin-NFAT signaling cascades in lymphocytes by promoting the association of STIM1 and ORAI1 during store-operated calcium entry (SOCE) in a protease-independent manner.
Synonyms: PSH1; IMP2; PSL4; MGC90402; MGC126674; MGC126676; DKFZP586C1324; MDHV1887; PRO4332
Tractability: Antibody: its Gene Ontology location is reachable by antibodies, with high confidence; UniProt predicts a signal peptide or a membrane-spanning region; the Human Protein Atlas places it where antibodies can reach. PROTAC: ubiquitination databases record sites on it.
Gene: Protein-coding gene on chromosome 12 (120,762,510 to 120,904,358, reverse strand). Ensembl gene ENSG00000157837.
Subcellular location: Endoplasmic reticulum membrane; Golgi apparatus; Membrane
Subcellular location (Human Protein Atlas): Plasma membrane; Vesicles
Gene Ontology:
Molecular function: aspartic endopeptidase activity, intramembrane cleaving; protein binding; protein homodimerization activity
Biological process: membrane protein ectodomain proteolysis; membrane protein proteolysis; positive regulation of calcineurin-NFAT signaling cascade; T cell receptor signaling pathway; positive regulation of cytosolic calcium ion concentration
Cellular component: cytoplasmic side of endoplasmic reticulum membrane; endoplasmic reticulum membrane; Golgi apparatus; Golgi-associated vesicle membrane; lumenal side of endoplasmic reticulum membrane; membrane; plasma membrane; rough endoplasmic reticulum; endoplasmic reticulum-Golgi intermediate compartment membrane
Genetic constraint (gnomAD): Loss-of-function variants: 3 observed, 31.1 expected, observed/expected ratio (o/e) 0.0965, 90% interval 0.043 to 0.25. The upper end of that interval is the gene's LOEUF score, 0.25, which puts it in group 1 of 6, group 1 being the genes least tolerant of losing a copy. Missense variants: 206 observed, 423.97 expected, observed/expected ratio (o/e) 0.49, 90% interval 0.43 to 0.55. Synonymous variants: 179 observed, 167.92 expected, observed/expected ratio (o/e) 1.07, 90% interval 0.94 to 1.21.
Homologues: Orthologues: chimpanzee SPPL3 (100% identical), mouse Sppl3 (100% identical), rabbit SPPL3 (99% identical), pig SPPL3 (99% identical), rat Sppl3 (99% identical), dog SPPL3 (99% identical), guinea pig SPPL3 (98% identical), macaque SPPL3 (95% identical), tropical clawed frog sppl3 (94% identical), zebrafish sppl3 (93% identical), Drosophila melanogaster SppL (64% identical). Paralogues in human: SPPL2B (29% identical), SPPL2C (27% identical), SPPL2A (26% identical), HM13 (20% identical).
Diseases named in the same sentence as SPPL3 in open-access papers:
SPPL3 is named in the same sentence as 12 diseases in open-access papers, as found by Europe PMC text mining. Sharing a sentence is not in itself a finding about the gene and the disease. The quoted sentences say what the papers report.
breast carcinoma (2 papers, 2020 to 2024). "SPPL3 is localized in the Golgi apparatus and widely expressed in humans; it is involved in the regulation of the immune system and tumor defense, and is listed as one of the genes that increase the risk of breast cancer." (PMID 38612746, 2024). "SPPL3 could indeed be involved in tumorigenicity as some single nucleotide polymorphisms (SNPs) in the coding region of SPPL3 have recently been linked to breast cancer as a risk factor." (PMID 33381526, 2020).
depression (1 paper, 2023). "For example, while SPPL3 and TCF4 have been associated with T2D and depression (as well as various other psychiatric traits), an association with CAD has not yet been reported." (PMID 37390107, 2023).
diffuse large B-cell lymphoma (1 paper, 2022). "To validate that resistance was not unique to ALL, we disrupted SPPL3 in the CD19 + diffuse large B cell lymphoma line OCI-Ly10." (PMID 35690611, 2022).
melanoma (1 paper, 2021). A malignant, usually aggressive tumor composed of atypical, neoplastic melanocytes. "This occurred through a transfer of ADAM10-activating SPPL3 through melanoma cell dendrites connecting with keratinocytes." (PMID 34502327, 2021).
Tetralogy of Fallot (1 paper, 2024). A congenital cardiac malformation comprising pulmonary stenosis, overriding aorta, ventricular septum defect, and right ventricular hypertrophy. "In line with this, circ-SPPL3 was shown to be a candidate biomarker for CHD tetralogy of Fallot." (PMID 39272989, 2024).
thyroid diseases (1 paper, 2023). "Novel TSH sentinel variants associated with thyroid diseases also implicated relatively understudied putative causal genes, such as SPPL3 and SDCCAG8." (PMID 37872160, 2023).
tumor (8 papers, 2020 to 2025). "The impact of loss of SPPL3 and an elevated nsGSL profile in tumor cells on innate immune recognition remains to be elucidated." (PMID 39655358, 2025). "Previously, we demonstrated that the loss of SPPL3 in tumor target cells reduced effector cytokine production and tumor cell clearance by αβ T cells due to nsGSL‐mediated shielding of HLA‐I." (PMID 39655358, 2025). "Together, the data show that the loss of SPPL3 and subsequent upregulation of nsGSLs by tumor cells protect them from elimination by γδ T cells and promote CD69 upregulation by γδ T cells." (PMID 39655358, 2025). "Underscoring the potency of SPPL3 as a regulator of cellular glycosylation, numerous unbiased cell-based genetic screens have since linked loss of SPPL3 to overt phenotypes such as glycosylation-dependent tumor immune evasion." (PMID 39587297, 2024). "Upon decreased expression or loss of SPPL3 by tumor cells, the cumulative immune escape effect may therefore involve both adaptive and innate antitumor immunity." (PMID 39655358, 2025). "Next, we investigated whether the loss of SPPL3 in target cells has an effect on neutrophil functionality, another innate immune cell type that is described to mediate antitumor reactivity through trogocytosis of cell membrane fragments from tumor cells." (PMID 39655358, 2025). "The link between regulation of N‐glycosylation by SPPL3 and decreased sensitivity of tumor cells to NK cell activity has been described." (PMID 39655358, 2025). "Here, we identify the involvement of SPPL3 in the actual killing of tumor cells by γδ T cells, which was mediated by downstream nsGSL synthesis as additional knockout of B3GNT5 reestablishes killing." (PMID 39655358, 2025). "We showed that tumor cells that lack SPPL3 possess the ability to evade innate immune responses mediated by NK cells, γδ T cells, and neutrophils." (PMID 39655358, 2025). "Loss of SPPL3 results in hyperglycosylation of CD19, an alteration that directly inhibits CAR T cell effector function and suppresses anti-tumor cytotoxicity." (PMID 35690611, 2022). "Thus, SPPL3 expression by tumor cells alters crosstalk with immune cells through the receptor–ligand interactome thereby driving escape not only from adaptive but also from innate immunity." (PMID 39655358, 2025). "Altered N‐glycosylation of ligands on tumor cells may be important for recognition by NK cells and may explain the lower NK cell‐mediated cell death of SPPL3−/− compared to WT NALM6 cells presented in this work." (PMID 39655358, 2025). "Therefore, expression of SPPL3 by tumor cells influences crosstalk between immune cells through a multitude of receptor–ligand interactions thereby driving escape not only from adaptive but also from innate immunity." (PMID 39655358, 2025). "B3GNT5 produces nsGSL on tumor cells which is regulated by SPPL3." (PMID 39655358, 2025). "From SPP's participation in tumor progression and survival, to SPPL3's regulation of protein glycosylation and SPPL2c's control over cellular calcium stores, various crossovers between proteolytic activity of intramembrane proteases and cell signaling will be described." (PMID 33381526, 2020). "This suggests that the combined therapy impairs tumor cell survival strategies such as DNA damage response, metabolic maintenance, and immune function (including CCR3, SPNS3, SPPL3, and BTN2A2)." (PMID 41404060, 2025). "Together, regulation of complex N‐glycosylation, rather than glycosylation of GSLs, by SPPL3 contributes to sensitivity of tumor cells to NK cell activity." (PMID 39655358, 2025). "GSTM3 is not described to be involved in the recognition of tumor cells by immune cells, nor is there a known link to SPPL3." (PMID 39655358, 2025).
cancer (4 papers, 2022 to 2023). A tumor composed of atypical neoplastic, often pleomorphic cells that invade other tissues. "Another study demonstrated that loss of SPPL3 impaired the efficacy of TCR-driven recognition of cancer antigens by promoting hyperglycosylation of MHC-adjacent glycosphingolipids, thus sterically hindering MHC/TCR interactions." (PMID 35690611, 2022). "Recently, cancer cells subjected to selection for increased or decreased expression of MHC-I have been subjugated to forward genetic screenings, identifying a substantial number of new genes that are able to regulate MHC-I antigen presentations, including IRF2, PBAF, PRC2, and SPPL3." (PMID 37256225, 2023).
infection (1 paper, 2019). The state of being infected such as from the introduction of a foreign agent such as serum, vaccine, antigenic substance or organism. "Conversely, the top 12 downregulated genes, including fermitin family member 1 (FERMT1), signal peptide peptidase like 3 (SPPL3), and tetratricopeptide repeat domain 19 (TTC19), negatively correlated with VA1 infection." (PMID 31671153, 2019).
SPPL3 also shares sentences with these, for which no sentence is quoted: asthma (1 paper); colorectal cancer (1); hypothyroidism (1).